IDS (iduronate 2-sulfatase)
Description:
Lysosomal enzyme involved in the degradation pathway of dermatan sulfate and heparan sulfate.
Synonyms: SIDS; ID2S; MPS2
Tractability: Antibody: UniProt predicts a signal peptide or a membrane-spanning region. PROTAC: its protein half-life has been measured.
Gene: Protein-coding gene on chromosome X (149,476,988 to 149,521,096, reverse strand). Ensembl gene ENSG00000010404.
Subcellular location: Lysosome
Pathways (Reactome):
Disease: MPS II - Hunter syndrome (CS/DS degradation); MPS II - Hunter syndrome (HS-GAG degradation)
Metabolism: CS/DS degradation; HS-GAG degradation
Gene Ontology:
Molecular function: calcium ion binding; iduronate-2-sulfatase activity; protein binding; sulfuric ester hydrolase activity
Biological process: glycosaminoglycan catabolic process; carbohydrate derivative catabolic process; dermatan sulfate proteoglycan catabolic process; heparan sulfate proteoglycan catabolic process
Cellular component: lysosome; lysosomal lumen
Gene-disease validity (ClinGen):
ClinGen rates the evidence that IDS causes each of these diseases.
mucopolysaccharidosis type 2 (X-linked): Definitive. A lysosomal storage disease leading to a massive accumulation of glycosaminoglycans and a wide variety of symptoms including distinctive coarse facial features, short stature, cardio-respiratory involvement and skeletal abnormalities.
Homologues: Orthologues: chimpanzee IDS (99% identical), macaque IDS (97% identical), rabbit IDS (89% identical), guinea pig IDS (88% identical), dog IDS (87% identical), pig IDS (86% identical), mouse Ids (86% identical), rat Ids (85% identical), tropical clawed frog ids (64% identical), zebrafish ids (59% identical), Drosophila melanogaster Ids (43% identical). Paralogues in human: ARSL (22% identical), GALNS (21% identical), ARSD (21% identical), STS (21% identical), ARSF (21% identical), ARSA (20% identical), ARSH (20% identical), ARSI (20% identical), ARSJ (20% identical), ARSB (19% identical), SGSH (19% identical), ARSK (18% identical), and 4 more.
Diseases named in the same sentence as IDS in open-access papers:
IDS is named in the same sentence as 71 diseases in open-access papers, as found by Europe PMC text mining. Sharing a sentence is not in itself a finding about the gene and the disease. The quoted sentences say what the papers report.
Hunter syndrome (132 papers, 2007 to 2026). "Mucopolysaccharidosis type II (MPS II) is an X-linked recessive lysosomal storage metabolic disorder caused by pathogenic mutations in the iduronate-2-sulfatase (IDS) gene." (PMID 42158367, 2026). "Hunter syndrome, which is inherited as an X-linked recessive syndrome, is caused by a mutation in the iduronate sulfatase (IDS) gene." (PMID 41141082, 2025). "MPS II, also known as Hunter syndrome, is caused by mutations in the IDS gene on the X chromosome and is typically described by neurological deterioration." (PMID 41511290, 2025). "Mucopolysaccharidosis Type II is a hereditary lysosomal storage disease characterized by deficiency in the enzyme iduronate 2-sulfatase (IDS)." (PMID 40569981, 2025). "Mucopolysaccharidosis (MPS) type II, or Hunter syndrome, is an X-linked lysosomal storage disorder caused by a deficiency of iduronate-2-sulfatase." (PMID 40981299, 2025). "As an enzyme replacement therapy (ERT), idursulfase is often prescribed for mucopolysaccharidosis (MPS) II (Hunter syndrome), facilitating the degradation of glycosaminoglycans (GAGs) by replacing the deficient enzyme iduronate-2-sulfatase." (PMID 40510111, 2025). "The PRNP locus on chromosome 20 encodes the prion protein implicated in multiple neurodegenerative diseases, and IDS gene on chromosome X is associated with Hunter’s syndrome, a lysosomal storage disease." (PMID 39789389, 2025). "In contrast to other MPS types with autosomal recessive inheritance, mucopolysaccharidosis type II (Hunter syndrome OMIM #309900) is an X-linked disease caused by a mutation in the iduronate-2-sulfatase (IDS) gene." (PMID 38425718, 2024). "Iduronate-2-sulfatase (IDS) is a lysosomal enzyme whose mutations are associated with the onset of Hunter syndrome (Mucopolysaccharidosis type II), a rare X-linked lysosomal storage disorder (LSD)." (PMID 38627369, 2024). "Mucopolysaccharidosis type II (MPSII) is a pediatric lysosomal storage disease caused by deficiencies in the IDS (iduronate-2-sulfatase) gene resulting in accumulation of glycosaminoglycans, multisystem disease, and profound neurodegeneration in severe forms." (PMID 37920237, 2023). "MPS II, also known as Hunter Syndrome, is caused by an inherited mutation in the IDS gene encoding for the iduronate-2-sulfatase (IDS) enzyme, resulting in dermatan sulfate and heparan sulfate accumulation." (PMID 37601653, 2023). "Mucopolysaccharidosis type II (OMIM 309900) is a lysosomal storage disorder caused by iduronate 2-sulfatase (IDS) deficiency and accumulation of glycosaminoglycans, leading to progressive neurodegeneration." (PMID 38033460, 2023). "Mucopolysaccharidosis type II, also known as Hunter syndrome, is a rare X-linked recessive disorder caused by deficiency of the lysosomal enzyme Iduronate-2- Sulfatase (IDS), leading to progressive accumulation of Glycosaminoglycans (GAGs) in several organs." (PMID 35882106, 2022). "On the other hand, MPS type 2 (Hunter syndrome) is characterized by mutation of the iduronate-2-sulfatase gene (X-linked recessive transmission)." (PMID 36329518, 2022). "Mucopolysaccharidosis type II (Hunter Syndrome) is a rare, x-linked recessive, progressive, multi-system, lysosomal storage disease caused by deficiency of iduronate-2-sulfatase (IDS)." (PMID 35563245, 2022). "This Phase 1/2 clinical trial attempts to treat MPS II (mucopolysaccharidosis II) patients with mutations in the iduronate-2-sulfatase (IDS) gene by inserting a correct copy of the IDS gene into the albumin locus in hepatocytes." (PMID 36324900, 2022). "Mucopolysaccharidosis II (MPS II) is an X-linked LSD resulting from deficient activity of iduronate-2-sulfatase, an enzyme responsible for the catabolism of the glycosaminoglycans (GAGs) heparan and dermatan sulfate." (PMID 35226042, 2022). "MPSII, also known as Hunter syndrome, is caused by mutations in the gene encoding the lysosomal enzyme, iduronate 2-sulfatase (IDS)." (PMID 35745855, 2022).
Hunter syndrome (continued). "Mucopolysaccharidosis type II (MPS II), or Hunter syndrome (OMIM #309900) is an X-linked lysosomal storage disorder (LSD) caused by variants in the IDS gene, that encodes the iduronate-2-sulfatase enzyme." (PMID 34805285, 2021). "Mucopolysaccharidosis type II is an X-linked lysosomal storage disorder caused by mutations in the IDS gene that encodes the iduronate-2-sulfatase enzyme." (PMID 34805285, 2021). "Mucopolysaccharidosis type II (MPS II, Hunter syndrome) is caused by mutation in the gene encoding iduronate 2-sulfatase (IDS)." (PMID 33996898, 2021). "Hunter’s syndrome, also known as Mucopolysaccharidosis type II, is a rare and inherited pathology triggered by the deficiency of iduronate 2-sulfatase (I2S), an enzyme catalyzing the degradation of the glycosaminoglycans dermatan- and heparan-sulfate." (PMID 34502086, 2021). "Mucopolysaccharidosis type II (MPS II) is an X-linked multisystem disorder caused by mutations in the gene encoding iduronate 2-sulfatase (IDS)." (PMID 34193122, 2021). "Mucopolysaccharidosis type II (Hunter syndrome or MPS2) is an X-linked disorder caused by a deficiency in the lysosomal enzyme iduronate-2-sulfatase (I2S) leading to the accumulation of glycosaminoglycans (GAGs), dermatan sulfate and heparan sulfate." (PMID 34976050, 2021). "Mucopolysaccharidosis type II (MPS II) is a lysosomal storage disorder caused by deficiency of the iduronate-2-sulfatase (IDS) enzyme, resulting in cellular accumulation of glycosaminoglycans (GAGs) throughout the body." (PMID 34622797, 2021). "The rare case of Hunter syndrome in girls observed by the authors is due to a disease-associated variant in the IDS gene inherited from the mother and a deletion in the long arm of the X chromosome of paternal origin." (PMID 33676511, 2021). "Hunter syndrome (mucopolysaccharidosis type II) is a genetic disorder caused by a deficiency of iduronate 2-sulfatase." (PMID 33129321, 2020). "Mucopolysaccharidosis type II (MPS II) or Hunter syndrome is an X-linked recessive lysosomal storage disorder resulting from deficient activity of iduronate 2-sulfatase (IDS) and the progressive lysosomal accumulation of sulfated glycosaminoglycans (GAGs)." (PMID 32448126, 2020). "Based on the high level of urinary GAGs and the deficiency of IDS activity, a relationship seems to exist between these data and the phenotypic expression of Hunter syndrome, contrasting with what is reported in the literature such as in Filipino patients." (PMID 32448126, 2020). "Mucopolysaccharidosis type II is a lysosomal storage disorder caused by a deficiency of iduronate-2-sulfatase (IDS) and characterized by the accumulation of the primary storage substrate, glycosaminoglycans (GAGs)." (PMID 32707880, 2020). "The high level of urine GAGs and the deficiency of iduronate 2-sulfatase activity was associated with the phenotype expression of Hunter syndrome." (PMID 32448126, 2020). "Here, we document a human induced pluripotent stem cell (iPSC) line generated from dermal fibroblasts of a patient with Hunter syndrome containing a hemizygous mutation of a 1 bp insertion at nucleotide 208 in exon 2 of the IDS gene." (PMID 31071499, 2019). "The structural defect of chromosome X in the girl confirmed the hemizygous state due to the mutation in the IDS gene, which has led to the formation of the clinical phenotype of Hunter syndrome." (PMID 31046699, 2019). "Mucopolysaccharidosis II is caused by mutations in the deficiency of iduronate-2-sulfatase (IDS) gene and can lead to life threatening tissue and organ damage." (PMID 31637541, 2019). "Hunter syndrome is an X-linked disorder caused by a deficit of the lysosomal enzyme iduronate-2-sulfatase and is associated with many disorders." (PMID 31152267, 2019). "Single nucleotide mutations in the iduronate 2‐sulfatase (IDS) gene at Xq28 most commonly cause Hunter syndrome, which can cause developmental delays." (PMID 31254375, 2019).
Hunter syndrome (continued). "The purpose of this article is to demonstrate a rare case of Hunter syndrome in a girl caused by a mutation in the IDS gene inherited from the mother and the presence of the paternal chromosome X with partial deletion in the long arm region." (PMID 31046699, 2019). "Hunter syndrome (mucopolysaccharidosis type II) is a recessive X-linked disorder due to mutations in the iduronate 2-sulfatase (IDS) gene." (PMID 31046699, 2019). "Mucopolysaccharidosis type II (MPS II), also known as Hunter syndrome, is a devastating progressive disease caused by mutations in the iduronate 2-sulfatase (IDS) gene." (PMID 30042467, 2018). "Hunter syndrome is a lysosomal disease characterized by deficiency of the lysosomal enzyme iduronate-2-sulfatase (I2S)." (PMID 29862106, 2018). "Hunter syndrome is a rare but devastating childhood disease caused by mutations in the IDS gene encoding iduronate-2-sulfatase, a crucial enzyme in the lysosomal degradation pathway of dermatan sulfate and heparan sulfate." (PMID 28593992, 2017). "To date, 542 pathogenic mutations in the IDS gene have been identified in patients with Hunter syndrome." (PMID 28593992, 2017). "Many IDS gene mutations and IDS deficiencies have been studied in human populations which result in the lysosomal storage of glycoaminoglycans and Hunter syndrome, an X-linked chromosome disease, referred to as mucopolysaccharidosis type 2 (MPS2)." (PMID 28401457, 2017). "Hunter syndrome is a lysosomal storage disease caused by mutations in the enzyme iduronate-2-sulfatase (IDS)." (PMID 28593992, 2017). "Hunter syndrome is an X-linked mucopolysaccharide storage (MPS) disease due to deficiency of iduronate-2-sulfatase activity caused by mutations in the IDS gene (OMIM 309900)." (PMID 28018694, 2016). "Hunter syndrome is characterized by accumulation of the heparan sulfate and dermatan sulfate due to deficiency of iduronate 2-sulfatase." (PMID 28018694, 2016). "Hunter Syndrome is an X-linked lysosomal storage disorder due to the deficit of iduronate 2-sulfatase, an enzyme catalysing the degradation of the glycosaminoglycans (GAG) dermatan- and heparan-sulfate." (PMID 25231261, 2014). "Mucopolysaccharidosis II (MPS II, Hunter syndrome) is a rare X-linked lysosomal storage disorder caused by a deficiency of iduronate-2-sulfatase (IDS), involving in the catabolism of glycosaminoglycans (GAG)." (PMID 23497636, 2013). "Hunter syndrome (HS) is a lysosomal storage disease caused by iduronate-2-sulfatase (IDS) deficiency and loss of ability to break down and recycle the glycosaminoglycans, heparan and dermatan sulfate, leading to impairment of cellular processes and cell death." (PMID 24083598, 2013). "Single nucleotide mutations in the iduronate 2-sulfatase (IDS) gene at Xq28 most commonly cause Hunter syndrome but deletion of the IDS gene has been reported in Hunter patients." (PMID 23634718, 2013). "Single nucleotide mutations in the iduronate 2-sulfatase (IDS) gene at Xq28 most commonly cause Hunter syndrome while a CGG expansion in the FMR1 gene at Xq27.3 is associated with Fragile X syndrome." (PMID 23634718, 2013). "In the case of Hunter syndrome, the two sisters carrying mutations in the IDS gene had a brother who died of the disease." (PMID 23320174, 2012). "Mucopolysaccharidosis II (MPS II), or Hunter syndrome, is an X-linked lysosomal storage disorder caused by a deficiency in the enzyme iduronate-2-sulfatase." (PMID 22383073, 2012). "Mucopolysaccharidosis II (Hunter syndrome) is a rare inherited lysosomal storage disorder resulting from a deficiency of iduronate-2-sulfatase (I2S)." (PMID 22279584, 2012). "Mucopolysaccharidosis type II (MPS II, Hunter syndrome) is X-linked recessive lysosomal storage disorder resulting from the defective activity of the enzyme iduronate-2-sulfatase (IDS)." (PMID 21605424, 2011).
Hunter syndrome (continued). "Mucopolysaccharidosis type II (MIM 309900) is X-linked recessive lysosomal storage disorder caused by the deficient of the enzyme iduronate 2-sulfatase (IDS, EC 3.1.6.13)." (PMID 21605424, 2011). "Mucopolysaccharidosis type II or Hunter syndrome is rare and is caused by a deficiency of iduronate-2-sulfatase." (PMID 20504305, 2010). "Mucopolysaccharidosis II (MPS II or Hunter syndrome) is a rare genetic disease caused by deficiency of the lysosomal enzyme iduronate-2-sulfatase (IDS)." (PMID 21637564, 2010). "MPSII, also known as Hunter syndrome, is a rare monogenic disease caused by IDS gene mutation." (PMID 41584852, 2026). "Mucopolysaccharidosis Type II (MPS II) is an X-linked lysosomal storage disease characterized by deficiency in the lysosomal hydrolase iduronate 2-sulfatase (IDS), a critical enzyme in the breakdown of the glycosaminoglycans (GAGs) heparan sulfate and dermatan sulfate." (PMID 40569981, 2025). "Mucopolysaccharidosis (MPS) type II (Hunter syndrome) is a rare X-linked, recessive, lysosomal storage disorder caused by the deficit of the enzyme iduronate 2-sulfatase (IDS), resulting in accumulation of glycosaminoglycans (GAGs) impairing cellular function in multiple organ systems." (PMID 37670899, 2023). "Mucopolysaccharidosis type II (Hunter Syndrome) is a rare, x-linked recessive, progressive, multi-system, lysosomal storage disease caused by the deficiency of iduronate-2-sulfatase (IDS), which leads to the pathological storage of glycosaminoglycans in nearly all cell types, tissues and organs." (PMID 35563245, 2022). "We show the successful application of ancestral sequence reconstruction to enhance the activity of iduronate-2-sulfatase (IDS), thereby increasing its therapeutic potential for the treatment of Hunter syndrome-a lysosomal storage disease caused by impaired function of IDS." (PMID 33665572, 2021). "Mucopolysaccharidosis type II (MPS II, also known as Hunter syndrome) is an X-linked lysosomal storage disease caused by the disturbed enzymatic activity of iduronate 2-sulfatase (EC 3.1.6.13), a lysosomal enzyme involved in the degradation of glycosaminoglycans (GAGs)." (PMID 33925963, 2021). "Mucopolysaccharidosis type II (MPS II), or Hunter Syndrome, is an X-linked lysosomal storage disease caused by deficiency of iduronate 2-sulfatase (IDS), a lysosomal enzyme involved in the catabolism of the glycosaminoglycans (GAGs) heparan sulfate (HS) and dermatan sulfate (DS)." (PMID 32751752, 2020). "The purpose of this article is to demonstrate a rare case of Hunter syndrome in a girl caused by a mutation in the IDS gene inherited from the mother and the presence of chromosome X of paternal origin, partially deleted in the long arm region - 46,X,del(X)(q22.1)." (PMID 31046699, 2019). "Iduronate 2-sulfatase is associated with Hunter syndrome clinical disorder (mucopolysaccharidosis type II, MPS-II) in which patients may display, scoliosis." (PMID 30845169, 2019). "The clear penetration of iduronate-2-sulfatase into the cerebrospinal fluid and the dose response suggest that intrathecal delivery of iduronate-2-sulfatase may be suitable for treating the central nervous system manifestations associated with Hunter syndrome." (PMID 25836678, 2015). "Hunter syndrome is a very rare genetic life-threatening lysosomal storage disease characterized by the accumulation of glycosaminoglycans due to the deficiency of the enzyme iduronate-2-sulfatase." (PMID 24237580, 2013). "Hunter syndrome is caused by mutation in the gene encoding iduronate-2-sulfatase (IDS)." (PMID 22013531, 2012). "Hunter syndrome (mucopolysaccharidosis II [MPS II]) is characterized by a deficiency in iduronate-2-sulfatase, a key enzyme in the catabolism of glycosaminoglycans (GAGs)." (PMID 28243577, 2017).